ARHGAP11B (Rho GTPase activating protein 11B)
Description:
Hominin-specific protein that promotes development and evolutionary expansion of the brain neocortex. Able to promote amplification of basal progenitors in the subventricular zone, producing more neurons during fetal corticogenesis, thereby playing a key role in neocortex expansion. Promotes the proliferation of basal progenitors by inhibiting the mitochondrial permeability transition pore (mPTP): delays the opening of the mPTP via interaction with ADP:ATP translocase, thereby increasing mitochondrial Ca(2+) concentration and inducing glutamine catabolism, which is required for basal progenitor proliferation. Does not possess GTPase activator activity: the absence of GTPase activator activity is required to promote amplification of basal progenitors during neocortex development.
Synonyms: FAM7B1; B'-T; GAP (1-8)
Tractability: PROTAC: ubiquitination databases record sites on it.
Gene: Protein-coding gene on chromosome 15 (30,624,494 to 30,649,529, forward strand). Ensembl gene ENSG00000285077.
Subcellular location: Mitochondrion matrix
Pathways (Reactome):
Signal Transduction: CDC42 GTPase cycle; RHOA GTPase cycle
Gene Ontology:
Molecular function: GTPase activator activity; protein binding
Biological process: cerebral cortex development; L-glutamine catabolic process; negative regulation of mitochondrial membrane permeability; positive regulation of GTPase activity; regulation of small GTPase mediated signal transduction; signal transduction
Cellular component: mitochondrial matrix; cytosol
Genetic constraint (gnomAD): Loss-of-function variants: 14 observed, 26 expected, observed/expected ratio (o/e) 0.54, 90% interval 0.35 to 0.84. The synonymous counts are far from expectation, so gnomAD's model fits this gene poorly and the ratio says little. Missense variants: 245 observed, 313.75 expected, observed/expected ratio (o/e) 0.78, 90% interval 0.7 to 0.87. Synonymous variants: 82 observed, 110.87 expected, observed/expected ratio (o/e) 0.74, 90% interval 0.62 to 0.89.
Homologues: Orthologues: zebrafish arhgap11a (49% identical), tropical clawed frog arhgap11a (48% identical), Caenorhabditis elegans rga-3 (17% identical), Caenorhabditis elegans rga-4 (16% identical). Paralogues in human: ARHGAP11A (87% identical).
Diseases named in the same sentence as ARHGAP11B in open-access papers:
ARHGAP11B is named in the same sentence as 17 diseases in open-access papers, as found by Europe PMC text mining. Sharing a sentence is not in itself a finding about the gene and the disease. The quoted sentences say what the papers report.
microcephaly (2 papers, 2021 to 2023). A congenital or acquired developmental disorder in which the circumference of the head is smaller than normal for the person's age and sex. "Due to ARHGAP11B’s likely role in human neocortex development and evolution, it is conceivable that its mutation or deletion could contribute to microcephaly." (PMID 34063381, 2021). "Notably, due to their role in fetal human neocortex development and their (potential) involvement in microdeletion syndromes, the genes ARHGAP11B and NOTCH2NL are likely targets for mutations leading to microcephaly." (PMID 34063381, 2021). "Therefore, ARHGAP11B’s contribution to 15q13.3 microdeletion/microduplication syndrome as well as to microcephaly, in general, remains open." (PMID 34063381, 2021). "ARHGAP11B and NOTCH2NL genes exert important roles during fetal human neocortex development and most likely also contribute to microcephaly." (PMID 34063381, 2021).
bipolar disorder (1 paper, 2020). A disorder of the brain that causes unusual shifts in mood, energy, activity levels and the ability to carry out day-to-day tasks. "Our study supports the findings from the literature regarding the association of the PAK2, ARHGAP11B, and PRODH genes with schizophrenia and/or bipolar disorder." (PMID 33510659, 2020). "Our findings support the association of the PAK2, ARHGAP11B, and PRODH genes with schizophrenia and/or bipolar disorder." (PMID 33510659, 2020). "Furthermore, a pilot study of CNVs on the data set from a total of 3,414 patients with schizophrenia, 713 patients with bipolar disorder, and 3,215 controls, showed that CNVs affecting 15q13.2 (ARHGAP11B and FAN1 genes) appeared to be schizophrenia-specific." (PMID 33510659, 2020).
breast carcinoma (1 paper, 2023). "In our study, using the Kaplan-Meier plotter, we also investigated the correlation between the expression of ARHGAP11A and ARHGAP11B and OS possibility in different types of breast cancer." (PMID 38046902, 2023). "In the current study, we analyzed the expression levels of two RhoGAP genes, ARHGAP11A and ARHGAP11B, in The Cancer Genome Atlas (TCGA) breast cancer (BRCA) and also our 51 IDC tumors compared to their matched normal tissues using quantitative polymerase chain reaction (qPCR)." (PMID 38046902, 2023).
cervical cancer (1 paper, 2023). A primary or metastatic malignant neoplasm involving the cervix. "Moreover, based on TCGA cancer data given in Results, ARHGAP11A and ARHGAP11B are highly overexpressed in cervical cancers, another area where estrogen and progesterone play important roles." (PMID 38046902, 2023).
glioblastoma (1 paper, 2026). The most malignant astrocytic tumor (WHO grade IV). "Here, we show that ARHGAP11B expression correlates with glioma malignancy and is essential for glioblastoma cell proliferation, implicating a critical role of glutaminolysis in tumor growth." (PMID 42129945, 2026).
lung disease (1 paper, 2025). "The remaining 11 genes in the region encode proteins associated with neurologic disorders (APBA2, CHRFAM7A, MTMR10, FAN1), skin and eye pigmentation or development (OCA2, HERC2, TJP1, TRPM1), nephritis (ARHGAP11B, MTMR10, FAN1), and lung disease (ENTREP2, NSMCE3)." (PMID 40013929, 2025).
schizophrenia (1 paper, 2020). A major psychotic disorder characterized by abnormalities in the perception or expression of reality. "15q13.2 microduplication, including the ARHGAP11B gene, was classified as probably pathogenic according to the Schizophrenia Working Group of the PGC publication." (PMID 33510659, 2020).
tumor (3 papers, 2023 to 2026). "Next, we compared the expression level of two RhoGAP paralog genes (i.e., ARHGAP11A and ARHGAP11B) in tumor and normal breast samples of IDC cases and evaluated them in several reproductive, demographic, and clinicopathological factors among women with IDC." (PMID 38046902, 2023). "ARHGAP11B expression was higher in tumor tissues, and its overexpression in the tumor samples predicted a poor prognosis." (PMID 36701707, 2023). "Furthermore, it was revealed that ARHGAP11B (P = 0.0006) was significantly upregulated in tumor samples versus normal tissues." (PMID 38046902, 2023). "Regarding TCGA-BRCA tumor stages, our analysis revealed that ARHGAP11A and ARHGAP11B showed overexpression across BRCA cancer stages, indicating their role in tumorigenesis and invasion." (PMID 38046902, 2023). "For the second gene, ARHGAP11B, our results showed that this gene had overexpression in ER-positive and HER2-positive tumor samples." (PMID 38046902, 2023).
cancer (1 paper, 2023). A tumor composed of atypical neoplastic, often pleomorphic cells that invade other tissues. "Our TCGA data analysis revealed higher expression of ARHGAP11A and ARHGAP11B in various cancers comprising BCs." (PMID 38046902, 2023). "In our study, we first performed a bioinformatic investigation regarding the role of these two RhoGAP paralog genes (i.e., ARHGAP11A and ARHGAP11B) in BC and different cancers and their correlations with each other and with other genes in different cancers." (PMID 38046902, 2023). "Moreover, our data found that ARHGAP11A and ARHGAP11B were also overexpressed in almost all TCGA cancers, representing their possible protooncogenic role." (PMID 38046902, 2023).
infection (1 paper, 2022). The state of being infected such as from the introduction of a foreign agent such as serum, vaccine, antigenic substance or organism. "In the 72 h infection group, the mRNA expression was up-regulated and the protein expression was down-regulated in seven groups, namely the TNXB, NFIA, PROC, SPIN1, NR2C2 nuclear receptor subfamily 2 group C member 2, Carboxypeptidase D and ARHGAP11B." (PMID 36496794, 2022). "In the 72 h infection group, the mRNA expression was up-regulated and the protein expression was down-regulated in 7 groups, namely the TNXB, NFIA, PROC, SPIN1, NR2C2 nuclear receptor subfamily 2 group C member 2, Carboxypeptidase D and ARHGAP11B." (PMID 36496794, 2022).
neurodegenerative disease (1 paper, 2024). A disorder of the central nervous system characterized by gradual and progressive loss of neural tissue and neurologic function. "In this brief Opinion Article, I would like to draw attention to the human-specific gene ARHGAP11B, which exhibits properties that could potentially be beneficial in the treatment of neurodegenerative diseases." (PMID 39664945, 2024). "Hence, ARHGAP11B fulfills a key criterion for its potential therapeutic application in neuron replenishment strategies for the treatment of neurodegenerative diseases—the ability to induce in vivo the self-renewal of those progenitor cells that generate cortical neurons." (PMID 39664945, 2024).
ARHGAP11B also shares sentences with these, for which no sentence is quoted: cognitive decline (1 paper); Ductal Carcinoma (1); encephalitis (1); glioma (1); nephritis (1); neurologic disorders (1).